FOXP3 (forkhead box P3)
Diseases named in the same sentence as FOXP3 in open-access papers (continued):
Sharing a sentence is not in itself a finding about the gene and the disease.
tumor (continued). "This means that FOXP3+ Treg cells maybe play a crucial in the tumor progression of OC." (PMID 41008548, 2025). "Furthermore, garcinol’s ability to interfere with FOXP3 acetylation could diminish the regulatory T-cell (Treg) suppressive capacity, thereby alleviating immunosuppression within the tumor microenvironment." (PMID 41303402, 2025). "In addition to macrophages, CD8+ cytotoxic T cells and their counterparts, FoxP3+ regulatory T cells, are another very interesting group of inflammatory cells that expressed an unexpected prognostic relevance in the normal tissue surrounding the tumor." (PMID 40498004, 2025). "Notably, the spatial co-localization of CD68+ tumor-associated macrophages (TAMs) with FOXP3+ Tregs has been strongly associated with reduced ICIs efficacy, with non-nuclear FOXP3 expression further compromising therapeutic outcomes." (PMID 40303413, 2025). "Further characterization of these immune cells is required to determine whether they represent pro-or anti-tumor infiltrate, however our finding that Treg-like CD4 + FoxP3+ cells were more prevalent in tumors bearing E. faecalis indicates that at least a portion of the infiltrate was pro-tumor." (PMID 41322090, 2025). "In microglia–T cell interactions, CX3CR1-dependent CXCL10 expression mediates microglial recruitment to the tumor site, where they implement T cell suppression through multiple immune checkpoints, including PD-1, cytotoxic T lymphocyte-associated protein 4 (CTLA-4), and forkhead box P3 (Foxp3)." (PMID 40948940, 2025). "The lymphocytes associated with the tumor immune microenvironment (TIME) are represented by all major subpopulations, including: CD20+ B-cells, CD3+CD4+ helper T-cells, CD3+CD8+ cytotoxic T-cells and the forkhead box P3-positive (FOXP3+) regulatory T-cells (Tregs)." (PMID 40725022, 2025). "Finally, CD4 + FOXP3 + (T-regulatory) cells were the least abundant cell population in the tumor." (PMID 39751643, 2025). "Furthermore, significant correlations emerged among FAP + CAFs, TILs, and CD68 + cells, and the co-occurrence of elevated FAP + CAFs, T-cytotoxic (CD8 +), T-regulatory (CD4 + FOXP3 +) cells, and macrophages (CD68 +) at the tumor center were independently associated with worse CSS." (PMID 39751643, 2025). "Thus, Foxp3 protein depletion was as effective as TREG cell ablation at inhibiting tumor growth." (PMID 40478934, 2025). "The Tip60–Foxp3 interaction enhances both the stability and transcriptional activity of Foxp3, where Tip60 acetylates Foxp3, preventing its polyubiquitination and degradation, ensuring increased protein levels, which promotes the suppressive Foxp3 Treg functions, helping drive tumor immunity." (PMID 39123405, 2024). "Foxp3 expression knockdown may stop in vivo tumor growth, according to experiments." (PMID 38602556, 2024). "Furthermore, metformin decreased IL-10+ and FoxP3+ Tregs, along with Gr-1+ myeloid-derived suppressor cells (MDSCs) in spleens, and in tumor tissue, it decreased IL-10+ and FoxP3+ Tregs, Gr-1+, NF-κB+, and iNOS+ MDSCs, and iNOS+ dendritic cells (DCs), while increasing the DCs quantity." (PMID 38892058, 2024). "Additionally, there has been ongoing debate regarding the role of FoxP3 in tumor development, whether it acts as a promoter or inhibitor." (PMID 39010095, 2024). "Although developing a better understanding of tumor-infiltrating Foxp3 + lymphocytes (Foxp3 + TILs) might provide essential knowledge to predict response to immunotherapy and prognosis, our current knowledge about Foxp3 + TILs is inadequate." (PMID 38402536, 2024).
tumor (continued). "In this study, we found that a high infiltration of CD8 + T cells coupled with low levels of FOXP3 + T cells in the tumor stroma may aid in selecting patients who are clinically responsive to chemotherapy, undergoing the influence of host pretreatment immune status on chemotherapy effectiveness." (PMID 39004706, 2024). "However, the natural state and functional role of FOXP3 positive tumor epithelial cells remain unknown." (PMID 38047300, 2024). "Moreover, it may downregulate PD-L1 expression on vascular endothelial cells through the inactivation of AKT pathway, thereby improving the ratio of CD8 T cells/FoxP3 T cells inside the tumor and remolding the immune microenvironment." (PMID 39220648, 2024). "Therefore, we next checked whether the expression of forkhead box P3 (Foxp3), a marker for regulatory T cells (Tregs), which suppress the immune response, was altered in formalin-fixed primary tumor tissues obtained from wild-type and Mbd2-deleted PyMT mice." (PMID 38556549, 2024). "The aim of this paper is to present the following medical hypothesis: CD137 and Eomes constitute a specific T cell activating axis, which results in the reprogramming of TREG into effector CD4 + FoxP3 + T cells and the tumor-specific activation of CD8 + T cells." (PMID 38355394, 2024). "The better outcomes observed in the FoxP3 +-high subgroups may be related to generalized heightened tumor inflammation, especially given the positive correlation between higher levels of FoxP3+ cells in the TME and higher CD8+ TILs and four-gene inflammation score." (PMID 39025948, 2024). "Immune cells with anti-tumor effects typically include M1 macrophages, cytotoxic CD8+ T lymphocytes, natural killer (NK) cells, and neutrophils, while M2 macrophages, Forkhead box protein P3 (FOXP3)+ T cells, and CD4+ helper T cells are often associated with promoting tumor growth." (PMID 38716256, 2024). "However, the exact effect on Foxp3+ cells within the tumor microenvironment remains elusive." (PMID 39737964, 2024). "Moreover, the Fe2+ levels and intracellular lipid ROS levels in mouse tumor tissues showed a marked elevation, while the numbers of FOXP3+CD25+ and CD8+ Treg cells in tumors were reduced, which revealed that LINC00942 inhibits ferroptosis and induces immunosuppression (p < 0.001, n = 5)." (PMID 38353724, 2024). "The inconsistent function of tumor-FoxP3 may be attributable to alternative splicing and posttranslational modifications, that is, FoxP3 with exons 3 and 4 deleted has significantly reduced tumor suppressive ability, and phosphorylation of FoxP3 by Lck represses cell invasion." (PMID 39150932, 2024). "Furthermore, in mice, treated with the tobacco smoke carcinogen 4-(methylnitrosamino)-1- (3-pyridyl)-1-butanone (NNK) and lipopolysaccharide, the abundance of TAMs (M2 macrophages phenotype), PD-L1+ tumour cells, Foxp3+CD4+ T cells, and CD8+ T cells was higher compared with NNK-induced tumours." (PMID 38541208, 2024). "On the one hand, it may be due to the co expression of chemokines and other products such as Foxp3 and Helios produced by tumor cells and stroma in the TME of CRC, which can enhance the inhibitory characteristics of Treg more strongly than other molecules acting alone." (PMID 38919615, 2024). "In fact, Foxp3 is regarded as the most specific marker for regulatory Tregs, i.e., a T cell subset that plays a crucial role in maintaining immune homeostasis in physiological conditions but is also able to promote tumor immune evasion by suppressing anti-tumor lymphocyte functions." (PMID 38892447, 2024). "In addition, we can utilize the epigenetic regulation of Tregs, particularly the manipulation of methylation, histone modifications and post-translational modification of FOXP3, to abrogate its suppressive function while preserving its survival capacity for achieving anti-tumor efficacy." (PMID 39144146, 2024).
tumor (continued). "Therefore, we further used flow cytometry to analyze immune cell infiltration in endpoint tumors, indicating that the percentage of CD206+ ST2L+ M2 macrophages, M2/M1 ratio and CD4+ Foxp3+ Tregs were higher in tumor allografts from the cisplatin monotherapy group." (PMID 38778059, 2024). "In addition, genomic studies by other groups have shown that the Opn gene (Sppl) is one of the few significantly upregulated genes in stimulated Foxp3+ Tregs, and tumor-infiltrating Foxp3+ Tregs express higher levels of Spp1 compared to spleen and lymph node Foxp3+ Tregs." (PMID 39272810, 2024). "In addition, significantly fewer regulatory T cells (FOXP3+) were found in Snail1ME-KO tumours." (PMID 37516803, 2023). "Moreover, FOXP3 was reported to promote tumor growth by inducing EMT in NSCLC." (PMID 37085672, 2023). "Therefore, targeting immunosuppressive subtypes, primarily FOXP3+ Tregs, might promote anti-tumor immunity and enhance the efficacy of PD-1 blockade." (PMID 37024479, 2023). "Second, ANGPTL8 could also interact with PIRB in macrophages (Kupffer cells) to upregulate Fgr expression and drive macrophage polarization into the M2 phenotype to suppress anti-tumor immune responses by increasing the number of CD4+FOXP3+ and CD8+PD-1+ T cells in the tumor microenvironment." (PMID 37188659, 2023). "Furthermore, its anti-tumor immune responses encourage the depletion of FOXP3+CD4+ Tregs." (PMID 36721212, 2023). "Likewise, it has been suggested that changes in the percentage of peripheral CD4+ CD25+ Foxp3+ regulatory T cells, a cell subset in charge of maintaining immune tolerance in the tumor microenvironment, may be predictive of irAEs." (PMID 36900420, 2023). "Interestingly, T cells expressing FoxP3, a marker usually associated with a regulatory T cell phenotype (Treg) with inhibitory function on CD4+ T cells, were more abundant in GL261-CIITA tumors compared to GL261 parental tumor (FoxP3: 618 cells/mm2 in GL261-CIITA; 29 cells/mm2 in GL261)." (PMID 36993983, 2023). "Thus, tumor-infiltrating Foxp3 cells may affect the local immune responses and be associated with LN metastasis." (PMID 37958412, 2023). "Our results indicate that blockade of Foxp3 failed to affect the migration of MCF7 cells but exerted a strong inhibitory effect on the migration of HER2+ LM3 and TNBC MDA-MB-231 cells, suggesting that Foxp3 may elicit differential tumor intrinsic effects depending on the tumor molecular subtype." (PMID 37766222, 2023). "Therefore, exploring the expression and the biofunction of FoxP3 in RCC tumor cells may help physicians to make better decisions in the treatment modalities." (PMID 37569676, 2023). "Also, we observed that CD39 was more expressed in HC than in LC in the shared cluster of CD4+FOXP3+ T-cells (cluster #2) suggesting that CD39 could also be a marker of tumor-specific regulatory T-cells." (PMID 38057799, 2023). "The up-regulation of FoxP3 could facilitate the migration and invasion of ccRCC cell lines, activate the immune-suppression-related pathways, and attract more Tregs infiltrated into the tumor microenvironment." (PMID 37569676, 2023). "In our study, FoxP3 could facilitate a tumor immune-suppressed microenvironment showed by 786-O RNA-sequence data and TCGA data, and we found that more Treg cells could infiltrate into tumor tissues with an abundant expression of FoxP3." (PMID 37569676, 2023). "Of note, FOXP3-expressing Tregs are normally known to actively maintain self-tolerance and immune homoeostasis via their suppressive functions against various immune responses; however, their functions in cancer were found to be co-opted by tumor cells to escape immune surveillance." (PMID 37189549, 2023). "Furthermore, in the TME, FoxP3 is also expressed in tumor cells." (PMID 36980787, 2023).
tumor (continued). "Notably, decreases in the ratios of CD4+/CD8+, CD4+FoxP3+/T-bet+CD8+ and CD4+T-bet+/CD4+FoxP3+ TILs were observed during progressive tumour outgrowth, suggesting that the T cell infiltrate in MC38 tumours shifts toward a more pro-inflammatory composition during progressive outgrowth." (PMID 37153625, 2023). "However, the regulation of FoxP3 in tumor cells is largely unclear, especially in RCC." (PMID 37569676, 2023). "Our exploration revealing the positive correlation between occurrence of CSCs and Tregs encouraged us to further explore whether CSCs even though present in low numbers, can generate CD4+CD25+FOXP3+ immunosuppressive Treg cells from effector CD4+CD25− T lymphocytes during tumor initiation phase." (PMID 38038865, 2023). "To assess whether i.t. inoculation of Ad.P60 affected the content of Tregs in spleen and tumor, we used Foxp3-EGFP reporter C57Bl/6J transgenic mice that were engineered to express an IRESEGFP sequence inserted at the 3′ end of the Foxp3 gene (B6.Cg-Foxp3tm2Tch/J)." (PMID 37766222, 2023). "Furthermore, our study demonstrates that CD8 immunohistochemistry may act as an instrument to identify tumours infiltrated by possibly functionally differing FoxP3+ T cell subtypes." (PMID 35140715, 2022). "Thus, it is of interest to note that both macrophage and Foxp3(+) TIL density located within the tumor is seemingly associated to general non-OPSCC survival twenty years later." (PMID 36289746, 2022). "However, lactic acid may provide metabolic support to tumour-infiltrating FOXP3+ Treg cells in highly glycolytic TME." (PMID 36569832, 2022). "In addition, it has been shown that BLM elicits CD8+ T cell-mediated responses, enhances the production of IFN-γ by T cells, and induces the expansion of forkhead box P3+ (Foxp3+) regulatory T cells via the secretion of transforming growth factor β by tumor cells." (PMID 35563721, 2022). "Similarly, patients with a high Treg (FOXP3+) density in the tumor microenvironment had a worse OS." (PMID 35197968, 2022). "It is speculated that highly suppressive FoxP3+Helios+ Tregs could play harmful roles in inhibiting anti-tumor immune responses in the circulation, especially at CRC advanced stages, while these cells could be beneficial in controlling inflammation in the TME especially at CRC early stages." (PMID 36146549, 2022). "In addition, heterotopic tumors from CreERT2 mice showed diminished inflammation demonstrated by reduced presence of total leukocytes (CD45+ area), TAMs (CD68+ area), neutrophils (MPO+ cells), tumor-infiltrating lymphocytes, TILs (FOXP3+), as well as T regulatory cells, Tregs (FOXP3+CD4+ cells)." (PMID 35688943, 2022). "We found that tumor-associated neutrophils (CD66b) and NK cells (CD56) were more commonly found in primary tumors than in liver metastases, while tumor-associated regulatory T cells (Foxp3), macrophages (CD163) and IFN-γ were more commonly found in liver metastases (p < 0.05)." (PMID 36195882, 2022). "In addition to the typical expression of CD25, CD4, and FOXP3, Treg cells express a number of chemokine receptors and surface molecules, such as CTLA4, PD-1, and TIGIT, which are linked to anti-tumor immunity and may make them a direct target for ICI therapy." (PMID 35967424, 2022). "Notably, the SPHK1-MTA3 axis enhanced the tumor infiltration of CD4+CD25+FoxP3+ Tregs and F4/80+CD11b+CD206+MHC class II- M2-like tumor-associated macrophages, and this effect could be reversed by PD-1 mAb treatment." (PMID 36050478, 2022). "Thus, in this study, by showing the presence of FoxP3+ Tregs and HPV in patients with OSCC in Japan, part of the immune response localized to the area of the tumor was clarified, and the associations with survival prognoses and clinicopathological indicators were evaluated." (PMID 34319010, 2022). "However, in CRC, the high frequency of Tregs is associated with a better prognosis, which contradicts the negative association of FOXP3+ tumor-infiltrated Tregs in other cancers." (PMID 35463305, 2022).
tumor (continued). "In addition, co-immunoprecipitation results have further revealed molecular mechanisms for the role of FOXP3 in tumor proliferation and apoptosis, and an in vivo studies suggested that FOXP3 can inhibit tumor growth by suppressing c-Myc directly or by interacting with the Smad2/3/4 pathway." (PMID 36235242, 2022). "Furthermore, we found the compartmental localization of FOXP3+ T reg cells might influence the impact of tumor immunity." (PMID 35361730, 2022). "Studies have shown that high infiltration of FOXP3+ Tregs cells in DLBCL is associated with better prognosis, but these studies have targeted the entire FOXP3 population rather than the true Tregs cells (eTregs) that are essential for the impact of tumor immunity." (PMID 35601491, 2022). "FOXP3+ Treg cells may play an important role in regulating the balance of tumour inflammation." (PMID 36569832, 2022). "Interestingly, a study reported that 4-1BB agonist treatment induces a subset of CD4+Foxp3+ Tregs to eliminate virus-induced tumor cells in mice, and the addition of 4-1BB expression in CAR T cells with an intracellular CD28 costimulatory domain improves their proliferation and cytotoxicity." (PMID 35917188, 2022). "Currently, except for its inhibitive effect on topoisomerase, EPI is also an antagonist of Forkhead box protein p3 (Foxp3), which may hold the potential to regulate the immune microenvironment in tumor tissues and thus trigger the immunogenic cell death in tumor tissues." (PMID 36145556, 2022). "In this study, we found that a high frequency of CD4+FoxP3+Helios+ Tregs in blood was associated with shorter DFS, suggesting the potential role of this highly immunosuppressive Treg subset in inhibiting anti-tumor immune responses, and consequently worsening clinical outcomes." (PMID 35655158, 2022). "Tumor infiltrating effector T cells, which can recognize tumor associated antigens (TAA) and selectively eliminate cancer cells together with NK cells, are in a critical equilibrium with immunosuppressive CD4+CD25+Foxp3+ Tregs, providing one known mechanism determining tumor control vs. progression." (PMID 35615083, 2022). "Treg cells, defined as CD4+CD25+Foxp3+ T cells, are a subpopulation of lymphocytes that are crucial in maintaining tolerance to self-antigens and innocuous foreign antigens under physiological conditions, but can also be co-opted by tumor cells to avoid the host immune response." (PMID 36230505, 2022). "The overexpression of TGF-β in tumor cells exerts dual effects: regulating the expression of PD-L1 and VEGF and affecting biomarkers associated with the modulation of immune response and evasion, including Foxp3/Treg, MDSC, Th1/Th2 balance, and macrophage cells." (PMID 35628416, 2022). "In addition, the ratio of CD4+CD25+Foxp3+ cells may be correlated with immune tolerance and tumor cell survival." (PMID 35181676, 2022). "It has also been shown that Foxp3 may be expressed in tumor cells." (PMID 35326661, 2022). "While there are multiple regulators that have been identified, such as tumour-associated macrophages and myeloid-derived suppressor cells, in the context of ACT, a concerning mediator of the tumour microenvironment is CD4+ Tregs, which have been characterized as CD4+FOXP3+CD25+." (PMID 35158816, 2022). "What is more important, a complex TME may also affect the role of FOXP3 in tumor metastasis." (PMID 36235242, 2022). "Moreover, the combination of ICIs and chemotherapy could synergistically induce antigen-specific immunity and enhance the infiltration of CD8+, and CD4+FoxP3 T cells to the tumor microenvironment." (PMID 35911702, 2022). "In a study in Central Asia, HSYA was found to lower the expression of Foxp3 and Rorγt in tumour tissue in the spleen, enhance immunity in mice, and reduce liver tissue damage due to cisplatin chemotherapy, thereby regulating the tumour immune micro-environment and exerting an anti-cancer effect." (PMID 35795285, 2022).